HMGB1 (high mobility group box 1)
Diseases named in the same sentence as HMGB1 in open-access papers (continued):
Sharing a sentence is not in itself a finding about the gene and the disease.
COVID-19 (115 papers, 2020 to 2025). A disease caused by infection with severe acute respiratory syndrome coronavirus 2. "One of its major ligands, HMGB1, is significantly elevated in the serum of COVID-19 patients and is associated with disease severity and CRS development." (PMID 38165854, 2024). "HMGB-1 has been implicated in several studies demonstrating its utility as both a biomarker of COVID-19 prognosis and risk factor of developing long COVID symptoms." (PMID 38932366, 2024). "Platelet-derived HMGB-1+ EVs have been reported as markers of platelet activation and are associated with a poor prognosis in COVID-19 patients." (PMID 38069209, 2023). "Studies on COVID-19 patients demonstrated changes in damage associated molecular patterns (DAMPs) including high mobility group box 1 (HMGB1) and surfactant protein A (SP-A)." (PMID 37662953, 2023). "Plasma levels of HMGB1 are high in patients diagnosed with severe COVID-19, and a significant inverse association exists between serum levels of HMGB1 and clinical outcomes." (PMID 36944948, 2023). "Olmesartan is a potential candidate for preventing the development of renal fibrosis associated with COVID-19, and HMGB1 is an important therapeutic target." (PMID 37256223, 2023). "In the present study, we found that increased CRP, IL-6, KL-6, HMGB-1, and d-dimer levels and decreased platelet counts early after admission were associated with the start of MV due to COVID-19." (PMID 35204430, 2022). "Many chronic inflammatory diseases are characterized by increased levels of circulating HMGB1, perhaps of importance for the increased risk of severe outcomes in COVID-19 patients with inflammatory comorbidities." (PMID 35558368, 2022). "In conclusion, increased CRP, IL-6, KL-6, HMGB-1, and d-dimer levels and decreased platelet counts were associated with the start of mechanical ventilation due to COVID-19." (PMID 35204430, 2022). "Future studies should particularly focus on the practical clinical value of HMGB1 and IL-6, including developing a scoring system with plasma HMGB1 and IL-6 as biomarkers for early recognition of COVID-19 patients at risk for developing severe disease." (PMID 33939645, 2021). "In terms of clinical evidence, it has been reported that elevated serum HMGB1 on admission is associated with poor clinical prognosis of COVID-19 patients." (PMID 34177566, 2021). "Therefore, HMGB1 may be a potential therapeutic target in severe pulmonary inflammation, including coronavirus disease 2019 (Covid-19) caused by severe acute respiratory distress syndrome coronavirus 2 (SARS-CoV-2)." (PMID 33101293, 2020). "Many chronic inflammatory diseases are characterized by increased circulating HMGB1 levels, possibly of importance for the increased risk of severe outcome in COVID-19 patients with inflammatory comorbidities." (PMID 32380958, 2020). "In severe pulmonary inflammatory diseases, including coronavirus disease-2019 (COVID-19), HMGB1 is abundantly secreted by necrotic pulmonary epithelial cells and innate immune cells." (PMID 38725632, 2024). "Activated platelets secrete HMGB-1 and promote NETosis, and enhanced aggregate formation of activated platelets with monocytes and neutrophils has been linked to thrombotic complications in severe COVID-19." (PMID 36980378, 2023). "It would be of interest to clarify whether (and if so, to what extent) different HMGB1 protein isoforms and/or Hmgb1 gene polymorphisms, could contribute to different progression and outcome in COVID-19 patients (and refs. therein)." (PMID 35454134, 2022). "Moreover, IL-6 (an inflammatory cytokine), HMGB-1 (a late inflammatory mediator), and KL-6 (reflecting injury and/or remodeling of type II pneumocytes) were associated with outcomes in COVID-19." (PMID 35204430, 2022). "Additionally, HMGB1 levels were measured in hospitalised COVID-19 patients with mild disease or COVID-19 associated acute respiratory distress syndrome (ARDS) and compared with a non-COVID-19-ARDS group." (PMID 36251689, 2022).
COVID-19 (continued). "Increased HMGB1 has been associated with more severe COVID-19 clinical outcomes." (PMID 34444232, 2021). "Chloroquine-mediated alkalinization of lysosomes inhibiting HMGB1-caused lysosomal leakage is a plausible mechanism that might be beneficial for COVID-19 treatment to prevent lysosomal leakage." (PMID 32380958, 2020). "High levels of HMGB1 have been shown in acute lung injury caused by infectious and severe COVID-19 patients, therefore, it could be a therapeutic target for patients with severe COVID-19." (PMID 37264452, 2023). "Therefore, we investigated whether olmesartan has a protective effect on the renal damage associated with COVID-19, and demonstrated the role of HMGB1 in it." (PMID 37256223, 2023). "However, the role of HMGB1 in renal damage associated with COVID-19 is still unclear." (PMID 37256223, 2023). "Furthermore, it is also thought that the risk of COVID-19 infectivity may also be increased by HMGB1 induced during AR, CRS, and ECRS." (PMID 34445093, 2021). "Increased level of HMGB1 can induce proinflammatory cytokine (TNF, IL-1, and IL-6) release, and since chronic inflammatory diseases result in HMGB1 increase, the severity in COVID-19 patients with underlying inflammatory comorbidities could be correlated to HMGB1 levels." (PMID 32948238, 2020). "Elevated levels of AGER ligands such as AGEs, S100, and HMGB-1 have been found in COVID-19 patients with severe disease, and these levels were found to be significantly higher in patients with COVID-19." (PMID 40362649, 2025). "In severe COVID-19 patients, multiple DAMPs, including HMGB1 and S100 proteins, are significantly increased due to the massive release of inflammatory mediators and the occurrence of cell death." (PMID 38600309, 2024). "Despite this study, little is known about serum HMGB1 levels in COVID-19 patients who had moderate symptoms on hospital admission and in whom the disease had not complicated." (PMID 37685970, 2023). "In this study, we have shown that in the early stages of SARS-CoV-2 infection there is a significant increase in serum HMGB1 levels compared with uninfected subjects, suggesting a pathological link between HMGB1 and COVID-19." (PMID 37685970, 2023). "Compared to healthy controls, COVID-19 patients had significantly higher concentrations of HMGB-1+ EVs (15,443 [8548–36,240] vs. 1980 [1500–2688] EVs/μL)." (PMID 38069209, 2023). "In critically ill COVID-19 patients, serum HMGB1 is elevated and correlated with levels of inflammatory cytokines." (PMID 38022581, 2023). "Elevated serum HMGB1 levels have been reported in hospitalized COVID-19 patients with severe and critical illness and in COVID-19 patients suffering from headaches." (PMID 37685970, 2023). "Here, we characterized the cellular origin of PS-exposing EVs in plasma from COVID-19 patients as well as their association with inflammation- and coagulation-related parameters, including CRP, HMGB-1, PF4, and TF." (PMID 38069209, 2023). "Together with high mobility group box protein 1 (HMGB1), RAGE signaling causes a cascade in COVID-19 pathogenesis leading to increased ROS production via NADPH oxidase activation as a cause of neuropathogenesis." (PMID 37357527, 2023). "High-mobility group box 1 (HMGB1) also plays a role among the mediators of platelet-neutrophil interplay and high HMGB1 levels were shown to be associated with COVID-19 mortality." (PMID 37275917, 2023). "In COVID-19 for instance, dexamethasone can potentially modulate the HMGB1 signaling pathway in infected patients." (PMID 37662953, 2023). "In the era of COVID-19, HMGB1 is considered a possible major player in the SARS-CoV-2-related triggering of hypercytokinemia, cytokine storms, and immunothrombosis, underlying the development of acute lung injury (ALI) and ARDS." (PMID 37685970, 2023). "Animal experiments also suggested that DAMPs released from necrotic cells such as HMGB-1 are potential drivers of disease exacerbation in COVID-19-induced ARDS." (PMID 36507222, 2023).
COVID-19 (continued). "As a cytokine mediator, HMGB1 is released from immune cells such as monocytes, macrophages, and dendritic cells via a particular secretory route in COVID-19 patients." (PMID 36851766, 2023). "The correlation between serum concentrations of HMGB1 and HO-1 in COVID-19 patients was positive and statistically significant (r = 0.264, p < 0.001)." (PMID 37685970, 2023). "Clinical trials are urgently needed to test different TNF-α/NF-κB inhibitors or HMGB1 antibodies for treatment or prevention of severe COVID-19 cases." (PMID 35992691, 2022). "Recent data revealed that plasma/serum HMGB1 levels of patients suffering from inflammation-mediated disorders—such as COVID-19, cancer, and autoimmune disorders—correlate positively with disease severity and vice versa." (PMID 35454134, 2022). "RAGE ligands (AGE, S100A8/A9, S100B, amyloid-beta, LPA, HMGB1, C1q, suPAR) and sRAGE are elevated in CKD, COVID-19 and many of the co-morbidities that increase the risk of disease severity." (PMID 36017003, 2022). "A separate study showed that the expression of high mobility group box 1 (HMGB1)–DNA complexes is upregulated in NETs released by COVID-19 patients, suggesting that circulating NETs contain higher levels of DAMPs." (PMID 35309344, 2022). "The results showed that the level of pro-inflammatory cytokines, TNF-α, IL-6, IL-8, and IL-1β were significantly elevated in severe COVID-19 patients, but the alarmin molecules IL-1α and HMGB1 were marginally higher." (PMID 36585712, 2022). "HMGB1 has been shown to be increased by a factor of 5 in severe COVID-19 courses compared to mild courses and is therefore discussed as a potential biomarker for severe COVID-19 courses." (PMID 36251689, 2022). "The significantly high level of HMGB1 protein found in the serum of COVID-19 and patients with MIS-C supports its involvement in inflammatory manifestations, suggesting HMGB1 as a potential biomarker and therapeutic target in patients with severe illness." (PMID 35558368, 2022). "The higher HMGB1 level in the serum of patients after SARS-CoV-2 infection with respect to control subjects suggests a possible link between HMGB1 and COVID-19." (PMID 35558368, 2022). "HMGB1 in plasma/serum is a useful biomarker of the occurrence of inflammation-related diseases, including cancer and COVID-19." (PMID 35454134, 2022). "HMGB1 inhibitors are also promising drug candidates for the treatment of patients suffering from COVID-19." (PMID 35992691, 2022). "Accumulating evidence shows that serum HMGB1 level is a potential biomarker for COVID-19 infected patients." (PMID 35401579, 2022). "In the present study, we clarified the role of biomarkers that are elevated both immediately and later after tissue damage, such as HMGB-1, a late inflammatory mediator, in COVID-19 patients." (PMID 35204430, 2022). "More studies are required, yet these results are good premises for the use of PAM in inflammatory pulmonary diseases, including COVID-19, where extracellular HMGB1 is expected to play a crucial role." (PMID 36071400, 2022). "Highly elevated serum levels of HMGB1 are found in COVID-19 patients, which correlates with poor prognosis of these patients." (PMID 35356515, 2022). "The HMGB1 level was also found to be slightly elevated when we compared patients with a recent history of COVID-19 patients with healthy children." (PMID 35558368, 2022). "Plasma HMGB1 levels correlate with IL-6 levels and these markers combined predict the mortality of COVID-19 patients in ICU settings." (PMID 36017003, 2022). "Various HMGB1-antagonist are investigated to ameliorate HMGB1-mediated inflammation, relevant for COVID-19 treatment." (PMID 35723340, 2022). "Even in the current pandemic COVID-19, increased circulating HMGB1 levels were observed and crosstalk between the complement, contact, and coagulation systems contributed to severe pathological consequences of the infection." (PMID 35572583, 2022).
COVID-19 (continued). "The median of HMGB1 was also significantly higher in the children with post-COVID-19 compared with controls (p < 0.0001)." (PMID 35558368, 2022). "The significant high level of HMGB1 protein found in the serum of patients with COVID-19 and MIS-C confirms its role in driving inflammation and highlights its involvement in their pathogenesis and severe manifestation." (PMID 35558368, 2022). "In a recent study, COVID-19 patients admitted to ICU had higher levels of HMGB1 compared to healthy controls." (PMID 34539644, 2021). "Given the role of the TLR4/HMGB1 axis in the progression of pulmonary inflammation—including with cytokine storms occurring with COVID-19—our results indicate that leytragin is a promising therapeutic agent for the prevention of cytokine storm with COVID-19." (PMID 34616852, 2021). "Regarding the disease severity of COVID-19, a correlation with increased inflammatory responses is well-established and HMGB1 is a critical extracellular mediator in these inflammatory processes." (PMID 34384355, 2021). "Recent studies have also highlighted that HMGB1 is one of the important host factors for COVID-19 pathogenesis." (PMID 34384355, 2021). "Active release from stimulated macrophages and other innate immunity cells further contributes to the strongly increased plasma HMGB1 levels present in severe COVID-19 patients." (PMID 33975537, 2021). "Severe/critical COVID-19 patients had higher plasmatic NE, LL-37 and HMGB1-DNA complexes, whilst ISG-15-DNA complexes were lower in severe patients." (PMID 34685525, 2021). "In fact, patients with COVID-19 had augmented values of HMGB-1 and IL-33 while facing lung injury or fibrotic processes." (PMID 34042528, 2021). "The HMGB1-RAGE axis is expected to be overexcited in COVID-19 as necrotic respiratory epithelial cells contribute large amounts of extracellular HMGB1 and its cognate RAGE receptor is constitutively abundantly expressed in the lungs." (PMID 34439887, 2021). "Street, in a recent paper, highlighted the need to assay HMGB1 in serum samples from COVID-19 patients who have been affected differently and who, as a rule, receive different treatment." (PMID 34439887, 2021). "When we evaluated the NET protein cargo by confocal microscopy, LDG and NDG from COVID-19 patients showed a higher expression of HMGB1, ISG-15 and LL-37 in comparison with healthy donors." (PMID 34685525, 2021). "Serum HMGB1 in patient with severe COVID-19 is increased and exogenous HMGB1 induces the expression of SARS-CoV-2 entry receptor ACE2 in alveolar epithelial cells." (PMID 34445093, 2021). "In COVID-19 headache patients who are unresponsive to paracetamol, HMGB1 level was significantly elevated (989.3 ± 263.5 vs 514.7 ± 248.9, p < 0.001) whereas IL-10 level (16.1 ± 11.9 vs 19.4 ± 5.6 p = 0.017) was decreased." (PMID 34384355, 2021). "The problem of steric hindrance generated by molecules complex-bound to HMGB1 in vivo has here been exemplified in the context of COVID-19, SLE, and septic shock and must be resolved via the invention of improved tools for diagnostic and therapeutic purposes." (PMID 34943830, 2021). "In COVID-19, macrophages release inflammatory cytokines (e.g., HMGB1) that can induce a hyperinflammatory response, which can be fatal." (PMID 34444232, 2021). "It has been hypothesized that significant increases in the HMGB1 levels in the circulation are a primary mediator of the dysregulated inflammation in SARS-CoV2 (COVID-19) respiratory failure as increased serum HMGB1 levels are correlated with a worse outcome in COVID-19 infection." (PMID 34271850, 2021). "Alarmins are possible danger signals associated with COVID-19 and comorbidities, and S100A8/A9, high mobility group box 1 (HMGB1), and histones are considered potential therapeutic targets." (PMID 34682694, 2021).
COVID-19 (continued). "Recently, extracellular high mobility group box 1 (HMGB1) has been identified as an essential component of cytokine storms that occur with COVID-19; HMGB1 levels correlate significantly with disease severity." (PMID 34616852, 2021). "HMGB1 promotes inflammatory neutrophil extracellular traps and is suggested as a therapeutic targets in severe COVID-19." (PMID 34680058, 2021). "Our results indicated that it will be important to study the potential role of HMGB1 in COVID-19-related headache in related models to gain more insight into the headache mechanisms triggered by external sources, specifically in COVID-19." (PMID 34384355, 2021). "Recently, extracellular high mobility group box 1 (HMGB1) was identified as a mediator of inflammation in COVID-19." (PMID 34616852, 2021). "Taken together, it seems that there are exceptional problems regarding systemic HMGB1 quantification during acute COVID-19, due to yet undefined partner molecules attaching strongly to HMGB1 and causing steric hindrance for antibody recognition." (PMID 34943830, 2021). "It is therefore highly surprising that only a few papers are documenting robustly increased systemic amounts of HMGB1 during the acute stage of severe COVID-19." (PMID 34943830, 2021). "This view is supported by our recent analysis of plasma samples from 9 COVID-19 patients with severe hyperinflammation using ELISA methods that revealed HMGB1 levels within the normal range." (PMID 34943830, 2021). "COVID-19 patients with headache and pulmonary infiltration (n = 31) had significantly higher serum levels of HMGB1, IL-6, D-dimer." (PMID 34384355, 2021). "Based on the changes and direct pathological effects of HMGB1 in COVID-19, genetic inhibitors and pharmacological drugs are explored in the experiments." (PMID 34446699, 2021). "Serum HMGB1 is increased in patients with severe COVID-19 and exogenous HMGB1 induces the expression of SARS-CoV-2 entry receptor ACE2 in alveolar epithelial cells." (PMID 34445093, 2021). "There are presently almost 200,000 publications about COVID-19 listed on PubMed but only 40 of them investigated the role of HMGB1, out of which only 4 reports on elevated systemic HMGB1 levels in COVID-19 patients." (PMID 34943830, 2021). "We found that COVID-19 NETs have a higher expression of HMGB1, LL-37 and ISG-15 in comparison with healthy donors." (PMID 34685525, 2021). "A hyperexcited HMGB1-RAGE axis can be expected in COVID-19 since necrotic respiratory epithelial cells contribute with large amounts of extracellular HMGB1, and its cognate receptor RAGE is constitutively abundantly expressed in the lungs." (PMID 32380958, 2020). "Based on these observations we propose extracellular HMGB1 to be considered as a therapeutic target for COVID-19." (PMID 32380958, 2020). "Although HMGB1 is considered as a potential target for the treatment of COVID-19, the changes and direct pathological effects of HMGB1 in COVID-19 are still poorly understood." (PMID 33313438, 2020). "The focus of this review is a possible role of the proinflammatory, endogenous mediator high mobility group box 1 protein (HMGB1) in the pathogenesis of COVID-19." (PMID 32380958, 2020). "Naringin also inhibits the expression level of cyclooxygenase (COX)-2, inducible nitric oxide synthase (iNOS), IL-1β and IL-6 via suppressing high mobility group box 1 (HMGB1) in COVID-19." (PMID 33708124, 2020). "The serum assays of HMGB1 in COVID-19 patients were only a preliminary step for the subsequent in vitro studies of HMGB1 function." (PMID 33313438, 2020). "Since necrosis releases more HMGB1 than apoptosis, this indicates that HMGB1 levels are differentially regulated in male and female COVID-19 patients with higher levels in males that further contributes to the severity and high mortality in males." (PMID 32948238, 2020). "The information gathered from these case studies indicates that serum HMGB1 in COVID-19 patients positively correlated with disease severity." (PMID 33313438, 2020).